ABCB1 (ATP binding cassette subfamily B member 1)
Diseases named in the same sentence as ABCB1 in open-access papers (continued):
Sharing a sentence is not in itself a finding about the gene and the disease.
cancer (continued). "Taken together, these observations led us to hypothesize that ABCB1 may influence cancer patient survival independently of drug efflux." (PMID 33202946, 2020). "Since bosutinib is already approved for use in cancer patients, our findings that this kinase inhibitor enhances ABCB1 internalization could be of high translational value." (PMID 32056006, 2020). "This present study reports for the first time that a novel antimicrobial peptide could re-sensitize ABCB1 overexpression-mediated MDR cancer cells by directly inhibiting the efflux function of ABCB1 transporter." (PMID 32707710, 2020). "In some cancers, e.g., leukemia, ABCB1 and ABCG2 are commonly co-expressed." (PMID 33066132, 2020). "Finally, only one miRNA sequence, hsa-miR-4539, was selected as a potential unexplored anti-cancer therapeutic for the regulation of ABCB1." (PMID 32029822, 2020). "These transporters are present in more than 50% of cancer-presenting MDR phenotypes or can be induced by chemotherapy and encoded by multidrug resistance protein 1 gene (MDR1 or ABCB1) for the p-glycoprotein or the ABCG2 gene for the breast cancer resistant protein (BCRP)." (PMID 33396739, 2020). "Combining ABCB1 inhibitors with ABCB1 substrate drugs may re-establish the drug sensitivity in drug-resistant cells, thereby enhancing therapeutic effect in cancer patients." (PMID 33519482, 2020). "Here we reported RN486 could surmount ABCB1-mediated MDR effectively in drug resistant cancer cells." (PMID 32984343, 2020). "Systemic ABCB1 inhibition can therefore result in toxicity as a consequence of a modified body distribution of anticancer drugs (and other drugs that are co-administered for conditions other than cancer), xenobiotics, and other molecules." (PMID 31501742, 2019). "Consequently, ABCB1 expression and efflux activity were reduced, causing the reversal of the MDR phenotype in those cancer cells." (PMID 31921125, 2019). "Notably, several studies demonstrated that drug-induced transient downregulation of ABCB1 or ABCG2 is another common mechanism in which the multidrug-resistant cancer cells can become resensitized to chemotherapeutic drugs." (PMID 31905792, 2019). "Concerning transporter ABCB1, it was shown to transport paclitaxel out of cancer cells." (PMID 31248089, 2019). "ABCB1 overexpression in cancers contributes to reduced intracellular chemotherapeutics accumulation and brings about resistance against a wide variety of the recently available antineoplastic agents like taxanes (docetaxel), vinca alkaloids (vinblastine), and anthracyclines (doxorubicin)." (PMID 31921655, 2019). "Our mechanism study also indicated that midostaurin could increase the accumulation of certain substrate-drugs (doxorubicin and [3H]-paclitaxel) in ABCB1-overexpression cancer cells by targeting the function of ABCB1 transporter." (PMID 31275850, 2019). "Our results indicate that the overexpression of ABCB1 or ABCG2 is unlikely to reduce the susceptibility of cancer cells to TMP195." (PMID 31905792, 2019). "It has been observed that blocking ABCB1 or ABCG2 with the specific exogenous siRNAs can reverse multidrug resistance in diverse cancer cells; even more, the concomitant application of both siRNAs using a nanoparticle-facilitated delivery showed a synergic effect in breast cancer cells." (PMID 31878061, 2019). "This novel study also suggests that co-administration of midostaurin with certain substrate-chemotherapeutic drugs of ABCB1 may benefit cancer clinical treatment by circumventing MDR." (PMID 31275850, 2019). "Using selenocompounds, such as chemosensitizers, these compounds have been shown to inhibit the ABCB1 in cancer cells, and based on these results, our aim was to investigate the efflux pump inhibitory properties of these selenocompounds on the representative bacterial efflux system AcrAB-TolC." (PMID 31014009, 2019).
cancer (continued). "Thus, the efflux of drugs via apical‐out polarised ABCB1 is capable of protecting cancer cells from cell death due to cytotoxic drugs." (PMID 30306567, 2019). "Approximately 50% of human cancer cells express ABCB1 at an adequate amount to confer CDR." (PMID 35582584, 2019). "Midostaurin significantly sensitized ABCB1-overexpressing cancer cells KB-C2 and SW620/Ad300 to ABCB1 substrates (doxorubicin, paclitaxel, and colchicine), compared with their control resistance cells, and this sensitization occurred in a dose-dependent manner." (PMID 31275850, 2019). "Since both miR-129-3p and miR-129-5p are derived from the same precursor, and both mature miRNA strands are functionally different in cells, it is feasible that over-expression of the miR-129 precursor in cancer cells using vector systems triggers cytoprotective autophagy, but inhibits ABCB1 levels." (PMID 31861937, 2019). "Rapid alteration of ABCB1 expression may be a potential predictor of chemotherapeutic efficacy in cancer patients." (PMID 31830995, 2019). "We hypothesised that these hallmarks were due to the presence of a sub-population of cancer stem cells expressing the multi-drug efflux transporter ABCB1." (PMID 31311995, 2019). "ABCB1 expression levels could be enriched by neurosphere culture thus supporting its expression in a subpopulation of cancer stem cells." (PMID 31311995, 2019). "Collectively, these data suggest that, sensitive cancer cells could internalize these EVs by a clatherin- and dynamin 2-mediated manner, and accelerate ABCB1 recycling back to plasma membrane via decreasing the expression of Rab5." (PMID 31830995, 2019). "In clinics, these carcinomas showed resistance to related chemotherapeutic drugs such as taxanes, vinca alkaloids, epipodophyllotoxins, anthracyclines, and tyrosine kinase inhibitors, and these drugs are known as substrates of ABCB1." (PMID 31801248, 2019). "It indicated that combination of VS-4718 with antineoplastic drugs could attenuate MDR mediated by ABCB1 or ABCG2 in ABCB1- or ABCG2-overexpressing cancer cells." (PMID 30425643, 2018). "P-glycoprotein (ABCB1) is an ATP-binding cassette transporter that plays an important role in the clearance of drugs and xenobiotics and is associated with multi-drug resistance in cancer." (PMID 30545335, 2018). "LS-2-3j might be useful as a lead compound in drug discovery and development for ABCB1- or ABCG2-mediated MDR cancer treatment." (PMID 30544754, 2018). "Moreover, taxifolin re-sensitized the MDR cancer cell, KB-vin, to the chemotherapeutic agents by inhibition of ABCB1 expression and enhancing the apoptosis." (PMID 30469543, 2018). "Combating cancer-drug-resistance with phytochemicals inhibiting ABCB1 could therefore be a more promising strategy to overcome multi-drug resistance (MDR)." (PMID 28626426, 2017). "As ABCG2 expression in primary SCC is much lower than ABCB1, treatment of lung aggregate cultures with rhWnt5a induced changes in drug transporter pattern in vitro that was highly similar to what was detected in primary cancer samples of squamous histology." (PMID 28340578, 2017). "Indeed, inhibition of ABCB1 with complementary pharmacological and genetic approaches substantially diminished chemoresistance of cancer cells." (PMID 28796259, 2017). "ABCB1 is a polyspecific drug efflux pump, required for transport of physiological substrates and xenobiotics across certain tissues of the body, yet in cancer, this protein employs a survival response and becomes overexpressed in order to efflux chemotherapeutics." (PMID 28409029, 2017). "ABCB1, which shows overexpression in some cancers, is involved in a common resistance mechanism." (PMID 27822437, 2016). "However, the cancer cell lines showed substantial differences in the promoter methylation status of the ABCB1 and ABCG2 promoters." (PMID 27689338, 2016).
cancer (continued). "If the patient’s cancer cells have a limited ABCB1 expression and function, using an inhibitor could increase toxicity to the normal bone marrow compartment while having little impact on the leukemic cells, this means more harm than benefit." (PMID 28119610, 2016). "Therefore, modulating the function or expression of ABC transporters, especially ABCB1, has great clinical significance in cancer treatment." (PMID 27649127, 2016). "Taken together, these data indicate that secretome factors from PTX-resistant cancer cells with acquired cross-resistance can sufficiently influence MDR in first-line PTX-resistant cancers cells with impaired FOXO3a-regulated ABCB1 activity and can be predicted by TUBB3 feedback." (PMID 27284014, 2016). "Nevertheless, this study shows that it is feasible to downregulate ABCB1 in vitro and in vivo by simvastatin, which may act as a lead compound in novel anti-cancer therapies." (PMID 26319048, 2016). "ABCB1 knockouts and reversion of chemoresistance in CSCs could potentially improve the outcome of chemotherapy in cancer patients." (PMID 27454254, 2016). "Thus, the changes in ABCB1 promoter methylation can be triggered partly by FOXO3a overexpression and drugs, whereby cancer cells have acquired first-line resistance and cross-resistance." (PMID 27284014, 2016). "High ABCB1 levels represent an important cancer cell resistance mechanism." (PMID 26887049, 2016). "To examine whether PPD12 increases the accumulation of ABCB1 substrates in MDR cancer cells, we measured intracellular levels of ADM and Rho123 in the presence or absence of PPD12." (PMID 26824187, 2016). "The resistant cells exhibited enhanced proliferative, clonogenic capacity with significant up-regulation of P-glycoprotein (ABCB1), c-Myc, survivin, β-catenin and a putative cancer-stem-like signature with increased expression of CD44, whereas the loss of E-cadherin signifies induced EMT phenotype." (PMID 27045798, 2016). "Frequent aberrant DNA methylation of ABCB1 has been observed in highly drug-resistant and invasive cancers, making its hypomethylation-triggering factors desirable targets for transcription-based inhibition, including the regulation of histone acetylation to reverse MDR." (PMID 27284014, 2016). "In order to determine the reversal effect of osimertinib on ABCB1-mediated MDR in ABCB1-overexpressing human cancer cells, cell survival assays were performed in the presence and absence of osimertinib, using the parental KB-3-1 cell line and drug-selective KB-C2 cell line." (PMID 27649127, 2016). "In conclusion, PPD12 enhances the efficacy of substrate drugs in ABCB1-overexpressing cancer cells." (PMID 26824187, 2016). "Interestingly, overexpression of the ABCB1 gene in cancer cells induced resistance to chemotherapeutic agents." (PMID 27729266, 2016). "Furthermore, the level of ABCB1 gene expression was confirmed to be several-fold higher in drug-resistant cancer cells compared to normal and parental cells, which confirms the high level of drug resistance in these cells." (PMID 27284014, 2016). "This may indicate that cancer cell adaptation to ABCB1 substrates may not only result in increased ABCB1 expression but potentially also to further changes that increase the specificity of ABCB1 to certain substrates." (PMID 26887049, 2016). "Increased levels of ABCB1 are commonly found in intrinsically resistant cancers." (PMID 27689338, 2016). "We have previously shown that the 3-hydroxy-3-methylglutaryl coenzyme A (HMG-CoA) reductase inhibitor simvastatin directly inhibits ABCB1, alters the glycosylation of the transporter, and enhances the intracellular accumulation of doxorubicin with subsequent anti-cancer action." (PMID 26319048, 2016). "ABCB1 (P-glycoprotein) was the first eukaryotic ABC transporter to be identified on the surface of cancer cells where it acts as a multidrug resistance (MDR) efflux transporter that prevents the accumulation of chemotherapeutic drugs inside cancer cells." (PMID 26047617, 2015).
cancer (continued). "Taken together, these results suggest that lapatinib could increase accumulation of ABCB1 substrate chemotherapeutical agents not only in ABCB1 overexpressing cancer cells but also in normal liver cells." (PMID 26036634, 2015). "Furthermore, cetuximab markedly increased intracellular accumulation of doxorubicin (DOX) and rhodamine 123 (Rho 123) in ABCB1-overexpressing MDR cancer cells in a concentration-dependent manner." (PMID 26506420, 2015). "As we know irinotecan is an ABCB1 substrate, we hypothesized that cetuximab could effectively compete with chemotherapeutic agent binding to ABCB1 and thus increase intracellular drug accumulation in resistant cancer cells." (PMID 26506420, 2015). "First generation found ABCB1/MDR1/P-gp inhibitors, which included the calcium channel blocker verapamil and the immunosuppressant cyclosporine A, showed effective sensitization of cancer cells which were otherwise resistant to paclitaxel, doxorubicin, and other ABCB1 substrates." (PMID 26633515, 2015). "Therefore, inhibition of ABCB1 gained research focus in order to resensitize MDR cancer cells to chemotherapeutical agents." (PMID 26296969, 2015). "Moreover, ABCB1 is frequently found highly expressed on cancer cells playing an important role in cancer cell drug resistance." (PMID 25749379, 2015). "The roles of three ABC transporters (ABCB1, ABCG2 and ABCC1) in multi-drug resistance associated with the efflux of various hydrophobic compounds, including major anti-cancer agents, such as taxanes, anthracyclines and anti-metabolites, have been studied in some detail." (PMID 25860815, 2015). "Importantly, trametinib remarkably enhanced the effect of vincristine against the xenografts of ABCB1-overexpressing cancer cells in nude mice." (PMID 25915534, 2015). "Furthermore, the ABCB1 (MDR-1) gene can confer multidrug resistance in cancer cells via P-glycoprotein (P-gp), which belongs to the ATP-binding cassette family of transporters." (PMID 26175965, 2015). "AR-mediated gene regulation of potential txr genes may be less important in advanced cancer cells in which stable ABCB1 amplification is dominantly responsible for the multidrug resistance phenotype." (PMID 26318424, 2015). "In this paper, in vitro, in vivo and in silico experiments were conducted to determine whether afatinib could resensitize multidrug resistant cancer cells to conventional chemotherapy drugs by interacting with ABCB1 and to uncover its mechanisms." (PMID 26317651, 2015). "Many cancer cells express large amounts of ABCB1, which renders these cancers multi-drug resistant." (PMID 25197934, 2014). "The overexpression of ABCB1 has been shown to produce a primary effect in MDR to the chemotherapy of cancer and confer significant resistance to a wide variety of anticancer substrate drugs, such as anthracyclines, vinca alkaloids, taxanes, epipodophyllotoxins, imatinib mesylate and so on." (PMID 25268163, 2014). "On the other hand, previous study indicated that DNA methylation status was affluence by chemotherapy drug in cancer cell and alternation of DNA methylation pattern led to gene expression level change such as ABCB1 was hypermethylated in MCF7 compared to MCF7/ADR2 cell." (PMID 25401518, 2014). "On the other hand, treatment of human cancers with histone deacetylase (HDAC) inhibitors may result in expression of ABCB1 or ABCG2 or both." (PMID 25268163, 2014). "Recent studies indicated that ABCB1 expression was controlled by Wnt signaling in MDR cancer cells." (PMID 25401518, 2014). "In addition to this, nilotinib significantly potentiates the anti cancer activity of PTX in ABCB1, ABCC10 and DOX in ABCG2 tumor xenograft model." (PMID 25191874, 2014). "To test this hypothesis, we applied each of the CDKi in combination with daunorubicin to ABCB1-expressing cells, both genetically modified and cancer-derived, to evaluate whether CDKi can synergistically potentiate daunorubicin’s cytotoxic effects." (PMID 24376706, 2013).
cancer (continued). "Furthermore, haematopoietic stem cells express efflux transporters from the ABC family, mainly Pgp/ABCB1, which confers protection against xenobiotics including anti-cancer agents." (PMID 24070327, 2013). "ABCB1 is widely recognized for its role in multidrug resistance of cancer cells." (PMID 23593196, 2013). "ABCB1 has become an attractive molecular target and inhibitors of this efflux transporter are being sought to increase the bioavailability of drugs after oral administration or overcome drug resistance and sensitize cancer cells." (PMID 24376706, 2013). "ABCB1 has been studied as a potential therapeutic target in other cancers." (PMID 24069258, 2013). "HA has been shown to stimulate ABCB1 expression and ABCB1 activity in various cancer cell lines." (PMID 24124770, 2013). "Increased level of ABCB1 is common in cancer cells, such as colon and kidney cancers." (PMID 23349819, 2013). "This may explain why Abcb1 inhibitors have had little ability to reverse resistance to taxanes in cancer patients." (PMID 22225778, 2012). "The aim of the present work was to ascertain if genetic variants within the ABCB1 gene influence the risk of CRC, with particular attention to the role of putatively functional variants that have previously been shown to be associated with cancer risk." (PMID 22396794, 2012). "Furthermore, the ABC transporters (ABCG2, ABCB1) have been proposed to be expressed by quiescent cancer stem cells, which allows them to survive cytotoxic or targeted therapies leading to relapse." (PMID 23174366, 2012). "Previously, through the use of an extensive screening process, we found that vardenafil, a phosphodiesterase 5 (PDE-5) inhibitor significantly reverses MDR in ABCB1 overexpressing cancer cells, and its efficacy was greater than that of tadalafil, another PDE-5 inhibitor." (PMID 21552528, 2011). "For several types of cancer, ABCB1 overexpression may be the predominant factor in limiting the efficacy of chemotherapeutic agents." (PMID 20520719, 2010). "We further hypothesized that if uPAR-positive cells represent drug-resistant and clonogenic population in SCLC, they may express CD44 and MDR1 (ABCB1) genes, which are involved in development of cancer stem cell phenotype and multi-drug resistance." (PMID 17327908, 2007). "P-glycoprotein/multidrug resistance protein 1 (P-gp/MDR1/ABCB1), multidrug resistance-associated protein 1 (MRP1/ABCC1), and breast cancer resistance protein (BCRP/ABCG2) are the most significant ABC transporters clinically proven to be associated with multidrug resistance during cancer therapy." (PMID 41154409, 2025). "One study reported that increases in the m6A levels in ERRγ mRNA (estrogen receptor-related receptor) could trigger the splicing of precursor ESRRG mRNA to promote its expression, with the upregulation of ERRγ conferring chemoresistance to cancer cells through the upregulation of ABCB1 and CPT1B." (PMID 40000966, 2025). "Besides the high potency of erdafitinib against malignancies harboring FGFR2 mutations and other rearrangements, several recent studies have demonstrated its “off-target” effect to sensitize cancer cells to certain chemotherapies due to its ability to interact with ABCB1 and impair its function." (PMID 41154409, 2025). "For instance, ABCB1 (Pattern 7), a key multidrug resistance transporter, was downregulated at 80 ppm, implying that moderate deuterium depletion could potentially sensitize cancer cells to chemotherapy." (PMID 41303451, 2025). "Thus, the potent molecular interaction of docetaxel with ABCB1 and CYP1B1 may insinuate potential resistance of the cancer cells to docetaxel via increased expression of ABCB1 and CYP1B1." (PMID 38534761, 2024).